INS (insulin)
Diseases named in the same sentence as INS in open-access papers (continued):
Sharing a sentence is not in itself a finding about the gene and the disease.
type 2 diabetes (continued). "The main defect for MIDD is the m.3243 A > G variant, which comprises enhanced susceptibility to metabolic syndrome and type 2 diabetes, followed by mitochondrial dysfunction, insulin resistance, and beta-cell dysfunction." (PMID 39835172, 2025). "The connection between the emergence of type 2 diabetes and PC is associated with beta-cell dysfunction within the pancreas, leading to an impaired response in insulin secretion triggered by glucose." (PMID 40487412, 2025). "In obese type 2 diabetes stage, loss of pancreatic β cell mass and failure of the remaining β cell function cannot provide sufficient insulin to meet the needs of the body." (PMID 40066372, 2025). "Physical activity increases the risk of hypoglycaemia in individuals with type 2 diabetes when basal or basal-bolus insulin therapy is administered." (PMID 40186685, 2025). "Lactiplantibacillus plantarum has been successfully engineered to reduce production of imidazole propionate, which has been reported to be associated with type 2 diabetes by impairing glucose tolerance and insulin signaling." (PMID 40261411, 2025). "The failure of pancreatic β-cells to secrete insulin sufficiently to meet the increasing demand of glucose metabolism is defined as a major contributor to type-2 diabetes with the secondary loss of β-cells." (PMID 40703332, 2025). "At present, impaired maturation of β-cells, which includes alterations in insulin biosynthesis and its accumulation in secretory granules, is considered one of the possible causes of insulin deficiency in both type 1 and type 2 diabetes." (PMID 39860066, 2025). "Perturbed secretion of insulin and other pancreatic islet hormones is the main cause of type 2 diabetes (T2D)." (PMID 41145477, 2025). "The SURPASS-3 study compared weight loss in people with type 2 diabetes taking tirzepatide and those treated with insulin degludec." (PMID 41465455, 2025). "KEGG pathway enrichment analysis identified 354, 45, and 106 genes associated with Alzheimer’s disease (term ID: hsa05010), type II diabetes mellitus (term ID: hsa04930), and insulin resistance (term ID: hsa04931), respectively." (PMID 40869265, 2025). "Collectively, current evidence supports a strong association between altered sialylation and impaired insulin signaling, suggesting that altering sialylation of specific molecules is a potential target for the treatment of type 2 diabetes." (PMID 41301440, 2025). "vWAT accumulation is associated with insulin resistance, increased risk of type 2 diabetes, dyslipidemia, atherosclerosis progression, and mortality, while scWAT accumulation is associated with improved insulin sensitivity and reduced risk of type 2 diabetes." (PMID 40076419, 2025). "Glucolipotoxicity (the deleterious effect of elevated glucose and fatty acids on beta cell function) has long been proposed to underlie the gradual deterioration of insulin secretion during the course of type 2 diabetes." (PMID 40768044, 2025). "The vast majority of genetic loci associated with type-2 diabetes development are primarily linked with pancreatic β-cell development and function as well as insulin secretion." (PMID 41514592, 2025). "High levels of CD36 are linked to increased inflammation and impaired insulin signaling in conditions like obesity and type 2 diabetes." (PMID 41465460, 2025). "Nucleotide polymorphism (SNP) in DENN/MADD is associated with fasting hyperglycemia and type II diabetes because of impaired insulin release." (PMID 40812422, 2025). "Nutritional deficiencies during pregnancy and low birth weight result in the suboptimal development of insulin-producing cells in the pancreas, increasing susceptibility to metabolic disorders, including type 2 diabetes, later in life." (PMID 40362802, 2025). "The rise in HPS is caused by fat accumulation, resulting in impaired insulin signaling and ultimately leading to the development of type 2 diabetes mellitus." (PMID 39858445, 2025).
type 2 diabetes (continued). "It demonstrated that intensive combination therapy, targeting the distinct pathophysiological defects in type 2 diabetes was associated with favorable cardiorenal outcomes, compared to conventional insulin and sulphonylurea therapy." (PMID 40129946, 2025). "In patients with type 2 diabetes, 6 mm needles in insulin pens were associated with lower pain, greater patient satisfaction, higher patient adherence and overall better glycemic control compared to 8 mm needles." (PMID 40943792, 2025). "Increased resistance to insulin in the body is a hallmark of type 2 diabetes, which means that the amount of insulin generated is insufficient to meet the body’s metabolic requirements." (PMID 39775570, 2025). "The main cause of type 2 diabetes is the decrease in insulin sensitivity caused by the increase in fat distribution, blood lipid value, and exercise ability." (PMID 40362436, 2025). "Systematic reviews and observational studies have reported that moderate alcohol consumption enhances insulin sensitivity and reduces the risk of type 2 diabetes." (PMID 40777174, 2025). "At chromosome 10q25, the transcription factor 7-like 2 (TCF7L2) type 2 diabetes risk gene controls beta-cell function as well as insulin secretion." (PMID 40225541, 2025). "Type 2 diabetes (T2D) is a major health care challenge caused by a combination of insulin resistance in target tissues and insufficient insulin release from islet beta cells." (PMID 41145477, 2025). "Conversely, sufficient vitamin D levels achieved through sunlight exposure, diet, or supplementation correlate with lower incidence of type 1 diabetes, improved insulin sensitivity in type 2 diabetes, and possibly a reduced risk of GDM and its complications." (PMID 40863099, 2025). "We previously showed that each cluster of newly diagnosed type 2 diabetes had an unequal risk of developing diabetic retinopathy, nephropathy, and the requirement of insulin treatment." (PMID 40338056, 2025). "Type 2 diabetes (T2D), the most common type of diabetes, is caused by decreased insulin sensitivity and resistance." (PMID 40868918, 2025). "Type 2 diabetes is caused by defective insulin secretion by pancreatic cells and the inability of insulin-sensitive tissues to respond appropriately to insulin." (PMID 40807271, 2025). "Many of these genetic variants modulate type 2 diabetes risk through direct or indirect effects on insulin secretion." (PMID 41009753, 2025). "Diabetes mellitus type II is caused by a combination of insulin resistance and damage in insulin secretion." (PMID 39752479, 2025). "This study aimed to evaluate the association between CP, EAT volume, and coronary artery calcification (CAC) as markers of cardiovascular risk, on subjects with type 2 diabetes receiving insulin and dialysis." (PMID 40978759, 2025). "Disruptions in serum Ca balance have been linked to insulin dysfunction and glucose regulation abnormalities, potentially contributing to the onset of type 2 diabetes mellitus (T2DM)." (PMID 41019331, 2025). "Elevated nighttime cortisol levels promote glucose production and reduce insulin sensitivity, thereby increasing the risk of developing type 2 diabetes and obesity." (PMID 40076739, 2025). "These associations are mechanistically plausible because high insulin in type 2 diabetes and insulin‐like growth factors, each via their own receptor and interchangeably, promote pancreatic cell growth." (PMID 40129249, 2025). "The metabolic benefits of breastfeeding, such as improved glucose metabolism, insulin sensitivity, and lipid profile, contribute to a lower incidence of type 2 diabetes and cardiovascular risk factors in breastfeeding mothers." (PMID 40895147, 2025). "Recent reviews have shown that HIIT is superior to continuous aerobic exercise in improving insulin resistance and blood glucose control, particularly in individuals with type 2 diabetes or those at high risk of developing the disease." (PMID 40778279, 2025).
type 2 diabetes (continued). "Further functional genomic analyses will be useful to shed light on the biological mechanisms underlying the role of these novel associations in glucose and insulin regulation and in type 2 diabetes pathogenesis." (PMID 40025146, 2025). "Type 1 diabetes is an autoimmune disease where the body’s immune system attacks insulin-producing cells, while type 2 diabetes arises from insulin resistance or insufficient insulin production, often linked to lifestyle factors." (PMID 39854291, 2025). "Evening chronotypes have a higher risk of type 2 diabetes than morning or intermediate chronotypes due to, in part, insulin resistance." (PMID 40018087, 2025). "Insulin resistance is a metabolic disorder known as type 2 diabetes that is characterized by a progressive loss of adequate cell insulin production and a rise in blood sugar levels (hyperglycemia)." (PMID 40416402, 2025). "Previous studies have shown that impaired insulin secretion is associated with worsened glycemic variability in patients with Type 2 diabetes." (PMID 41497478, 2025). "Type 2 diabetes is a metabolic condition caused by insulin resistance and decreased insulin secretion." (PMID 39563945, 2025). "Further in-depth research on insulin secretion revealed a connection between the rs10830963-G allele and reduced early-phase insulin secretion, mirroring the impairment seen in patients with type 2 diabetes." (PMID 40428319, 2025). "Type 2 diabetes is associated with hypersecretion of somatostatin, which has implications for paracrine regulation of insulin and glucagon secretion." (PMID 39803760, 2025). "Diminished functional beta-cell mass is a key pathogenic mechanism underlying both type 1 and type 2 diabetes (T1D and T2D), precipitated by the progressive impairment of insulin secretion, loss of cellular identity, and ultimately, beta-cell death." (PMID 40612435, 2025). "Weight loss through diet, physical activity, and lifestyle changes in women with PCOS, especially those with obesity, can improve metabolic parameters, reduce the risk of type 2 diabetes, lower triglycerides, and enhance insulin sensitivity." (PMID 40283538, 2025). "Defects in microvascular insulin action and NO production and reduced endothelial compliance are a hallmark of metabolic disease and contribute to the aetiology of type 2 diabetes." (PMID 39503770, 2025). "Type 2 diabetes (T2D) is a metabolic disease characterized by the progressive loss of insulin secretion with different grades of insulin resistance and is considered the most common type of diabetes, representing more than 90% of all cases." (PMID 40869354, 2025). "In type 2 diabetes, insulin resistance is the primary cause, while impaired insulin secretion results from inflammation and hyperglycemia." (PMID 39861134, 2025). "Given his medical history of Type II diabetes, an elevated endogenous insulin level was believed to be the cause of hypoglycemia, and this was demonstrated by the significantly elevated C-peptide levels, 12.5 ng/mL (normal 0.5–2 ng/mL)." (PMID 41368518, 2025). "Type 1 and advanced type 2 diabetes are associated with hyperglycemia resulting from reduced insulin secretion by the pancreas." (PMID 40932945, 2025). "C16 and C18 ceramides are particularly associated with obesity, type 2 diabetes, and liver steatosis, with studies showing that disrupting C18 Cer synthesis improves insulin sensitivity and glucose tolerance in high-fat diet models." (PMID 40548377, 2025). "Type 2 diabetes is marked by chronic hyperglycemia (HG) due to insulin resistance or deficient secretion." (PMID 40375923, 2025). "Type 2 diabetes (T2D), which is more common and often associated with obesity, involves progressive β‐cell dysfunction alongside peripheral insulin resistance." (PMID 40919135, 2025).
type 2 diabetes (continued). "SCAT analysis, developed by Otani, has previously been applied to investigate factors causing Japanese patients with type 2 diabetes to hesitate in starting insulin therapy and to analyze interviews conducted by primary care physicians abroad." (PMID 41244761, 2025). "Hypomagnesemia has been associated with reduced insulin sensitivity and increased risk of type 2 diabetes." (PMID 40136609, 2025). "Skeletal muscle mitochondria are essential for maintaining cellular energy balance, and their dysfunction has been linked to reduced insulin sensitivity and the development of type 2 diabetes (T2D)." (PMID 40573101, 2025). "Recently, circulating BCFAs were also found to associate with insulin sensitivity and beta cell function in a longitudinal study including subjects with type 2 diabetes." (PMID 40010610, 2025). "The modulation of gut microbiota has also been linked to improvements in insulin sensitivity and glycemic control in patients with type 2 diabetes, highlighting its potential application in metabolic syndrome." (PMID 40901203, 2025). "Intranasal insulin also improved memory in patients with Type 2 Diabetes, a disease that doubles the risk for AD." (PMID 40006083, 2025). "We previously showed that global FATP2 deletion in genetic and inducible mouse models of type 2 diabetes was associated with markedly decreased plasma glucose and increased plasma insulin." (PMID 40956612, 2025). "Unlike type 1 diabetes, which is characterized by insulin deficiency, type 2 diabetes initially leads to increased insulin secretion as a compensatory response to elevated blood glucose levels, resulting in hyperinsulinemia." (PMID 40286055, 2025). "Type 2 diabetes (accounting for over 90% of cases) arises from insulin resistance coupled with an inadequate compensatory insulin secretion, often associated with obesity and a sedentary lifestyle." (PMID 40863099, 2025). "This is important since achieving optimal glycaemic control using insulin has been associated with a reduction in complications in both type 1 and type 2 diabetes and a reduction in all-cause mortality." (PMID 39854487, 2025). "Type 2 diabetes (T2D) is a group of metabolic disorders characterized by chronic hyperglycemia which caused by insufficient insulin secretion or defective insulin action." (PMID 41098781, 2025). "Given findings in humans that social isolation is associated with a higher risk of developing type 2 diabetes, this study investigated the impact of social isolation on glucose metabolism and insulin sensitivity." (PMID 39821966, 2025). "Because α-Linolenic acid (ALA) has been linked to enhanced insulin sensitivity and a decreased risk of type 2 diabetes, there is evidence that it helps glycemic control." (PMID 39940428, 2025). "Glucose homeostasis relies on tightly regulated insulin secretion by pancreatic β cells, and their dysfunction is a hallmark of type 2 diabetes." (PMID 39996055, 2025). "The association between AIP and type 2 diabetes in individuals with obesity is likely mediated by its reflection of lipid abnormalities commonly seen in insulin-resistant states." (PMID 40747310, 2025). "An upward shift in the relationship between IGFBP-1 and insulin has previously been reported in older men (63–81 years compared to 20–39 years), in GH deficiency and type 1 diabetes, and in type 2 diabetes." (PMID 40188287, 2025). "Physical activity also improves glucose tolerance and insulin sensitivity, potentially reducing the risk of type 2 diabetes." (PMID 40966607, 2025). "These include improvements in insulin sensitivity, modulation of gut hormone secretion, and reductions in systemic inflammation, all of which contribute to type 2 diabetes remission and reduced cardiovascular risk." (PMID 40868582, 2025). "Type 2 diabetes is caused by insulin, resistance in the patient’s body, where fat tissue, muscles, and liver cells no longer use insulin, and then the body gets the wrong instructions to secrete more insulin." (PMID 40362847, 2025).
type 2 diabetes (continued). "Two of the studies included even higher risk individuals, with pre-existing Type 2 diabetes comprising more than half the study sample for one, while the other was limited to individuals with a history of insulin-requiring gestational diabetes." (PMID 39861424, 2025). "In type 2 diabetes, a longer duration of disease and insulin use are associated with an increased risk; (Evidence level Ia), which is partly independent of BMD." (PMID 40921943, 2025). "Related studies have shown that the G risk allele in MTNR1B rs10830963 is associated with higher MTNR1B expression, leading to enhanced inhibition of insulin secretion by melatonin, impaired insulin secretion, and increased risk of type II diabetes." (PMID 41002997, 2025). "The remaining reported improvements in insulin sensitivity and a reduced risk of progression to type 2 diabetes with vitamin D supplementation." (PMID 40004770, 2025). "Disruption of insulin–leptin crosstalk contributes to central insulin and leptin resistance, a hallmark of obesity and type 2 diabetes." (PMID 41409607, 2025). "Reduction in mtDNA copy number in insulin-sensitive tissues, such as skeletal muscle and adipose tissue, is associated with impaired mitochondrial function and an elevated risk of developing type 2 diabetes." (PMID 40806527, 2025). "Age-related decline in adipose tissue function is closely associated with impaired insulin sensitivity and chronic low-grade inflammation, and these conditions contribute to type 2 diabetes (T2D) development in older adults." (PMID 41462520, 2025). "Weight loss has been shown to significantly improve insulin sensitivity and, therefore, decrease the risk of developing type 2 diabetes." (PMID 41041606, 2025). "Knockout of UCP2 in pancreatic β-cells enhances glucose-induced insulin secretion, while its overexpression inhibits this process, increasing the risk of type 2 diabetes in humans." (PMID 40686867, 2025). "When people who use insulin for Type 2 diabetes have a hospital admission and discharge, they are at risk of harm from incorrect, delayed, or missed insulin doses." (PMID 40696540, 2025). "This study clearly demonstrated that obesity, characterized by excessive fat accumulation, is associated with insulin dysfunction and the development of Type 2 diabetes." (PMID 40376699, 2025). "Common polymorphisms and rare heterozygous loss-of-function (LoF) mutations in SLC30A8 are associated with reduced risk of developing type 2 diabetes, a disease that is characterised primarily by impaired insulin secretion and sensitivity." (PMID 41020949, 2025). "Prolonged sitting has been shown to elevate postprandial glucose and insulin responses, contributing to insulin resistance and increasing the risk of type 2 diabetes (T2D)." (PMID 41464286, 2025). "The adipose tissue is critical for systemic insulin sensitivity and glucose homeostasis, with impairments in adipocyte function tightly linked to the onset of obesity and type 2 diabetes (T2D)." (PMID 41062857, 2025). "As a result, cells become less responsive to insulin, which is a significant risk factor in the pathogenesis of type 2 diabetes and other metabolic disorders." (PMID 40806527, 2025). "This investigation tried to find out how β‐sitosterol affected the production of insulin signaling molecules in the fat tissue of rats that were fed a high‐fat diet and sucrose to cause Type 2 diabetes." (PMID 41376823, 2025). "It is related to ameliorated insulin sensitivity and lipid profile in addition to a decreased risk of type 2 diabetes and cardiovascular diseases including myocardial infarction." (PMID 41272013, 2025). "The rs2237892 SNP at the KCNQ1 locus was previously shown to display parent-of-origin effects on type 2 diabetes risk and insulin secretion." (PMID 40175764, 2025).